EPCAM (epithelial cell adhesion molecule)
Diseases named in the same sentence as EPCAM in open-access papers (continued):
Sharing a sentence is not in itself a finding about the gene and the disease.
tumor (continued). "However, it has been well described that metastatic cells undergo epithelial-to-mesenchymal transition (EMT) and express varying to even undetectable amounts of EpCAM, implying that standard CSF-TC detection fails to capture a proportion of tumor cells." (PMID 40075672, 2025). "While this study provides a foundation for developing robust DST platforms, further research is needed to explore its applicability across diverse cases where targeting EpCAM for identification of tumor cells may not be suitable." (PMID 40525275, 2025). "In contrast, EGFR and EpCAM levels did not significantly differ across tumor grades." (PMID 40806559, 2025). "Although EpCAM is not a direct marker of metastasis, its expression pattern here may reflect the relative extent of tumor infiltration across different treatment groups." (PMID 40958869, 2025). "While surface markers such as CD44, CD133, aldehyde dehydrogenase 1 (ALDH1), and epithelial cell adhesion molecule (EpCAM) have been widely used to identify CSCs across various tumour types, they are not unique to CSCs and are often expressed in normal progenitor or differentiated cells as well." (PMID 41321388, 2025). "The two most promising examples include (a) BsE CD73 x EpCAM which binds and inhibits exosomal CD73 to suppress production of immunosuppressant adenosine and (b) BsE CD3 x PD-L1 which targets exosomal PD-L1 within the tumor microenvironment to guide cytotoxic T-cells towards tumor cells." (PMID 40037165, 2025). "Tumour epithelial cells were further reclustered into two distinct subclusters (Subcluster 1 and Subcluster 2), and DUSP9 was predominantly expressed in Subcluster 1, which was enriched with other oncofetal and stemness‐related genes such as AFP, GPC3, IGF2, ANPEP and EPCAM." (PMID 41383134, 2025). "CTCs with low or no EpCAM expression could serve as a valuable alternative for tumor analysis, even though they may be less prognostically significant compared to EpCAM high-expressing CTCs." (PMID 40076201, 2025). "However, for the processing of clinical samples, GEM devices functionalized with either anti-EpCAM or anti-EGFR were used to ensure the capture of DTCs of varying surface markers since we do not know the true identity of tumor cells in clinical samples." (PMID 40073025, 2025). "Furthermore, the exclusion of the EpCAM+/CD45+ cell subpopulation from the depleted cell fraction will not preserve the original MPE tumor heterogeneity and will fail to reliably reflect its drug sensitivity." (PMID 40525275, 2025). "Furthermore, EpCAM-CAR-T cells had a higher tumour inhibition rate in the EpCAM expression positive group than in the negative group (P < 0.05)." (PMID 39107717, 2024). "However, at the protein level, we did not observe any differences in EpCAM expression in BMDMs between groups of 4T1 tumor-bearing mice." (PMID 38355711, 2024). "Interestingly, additional anti-PD-1 treatment did not increase intratumoral EpCAM/GFPCAR T-cell density or anti-tumor efficacy, resulting in a similar growth pattern compared to animals receiving the IgG isotype control antibody." (PMID 39358663, 2024). "Additionally, calculation of tumour‐related epithelial markers (EPCAM, KRT8 and KRT19) for each spot in all samples revealed that tumour areas showed the highest epithelial scores compared to other areas, confirming the accurate identification of tumour areas." (PMID 39187937, 2024). "EpCAM (epithelial cell adhesion molecule) has also emerged as a promising target for epithelial-derived tumors, due to their EpCAM overexpression, exploiting it for NIR fluorescence-guided surgery, improving the precision of tumor resections in various types of cancer." (PMID 39766041, 2024).
tumor (continued). "In contrast, differentially expressed genes between CECs isolated using the cmHsp70.1 mAb- versus EpCAM mAb-based approach, such as ROCK2, STAT3 and CD82, are related to EMT, stemness and endometrial cell proliferation, which are regulated via up-regulated CD44/STAT3 signaling in tumor cells." (PMID 39519195, 2024). "It is noteworthy that concomitant anti-PD-1 treatment was not able to ameliorate tumor-induced T-cell exhaustion, resulting in similar growth patterns and overall survival rates between the EpCAM/GFPCAR T-cell/anti-PD-1 and EpCAM/GFPCAR T-cell/IgG-treated animals, respectively." (PMID 39358663, 2024). "Our recent work identified EpCAM-positive extracellular vesicles in the ascites of patients with advanced HGSC as potential prognostic biomarkers, capable of predicting early recurrence and suggesting a likelihood of more aggressive tumor biology and chemoresistance." (PMID 39337685, 2024). "In the reverse scenario, in EPCAM-negative compared to EPCAMhigh tumor spots following pathways were upregulated: Hallmark_epithelial_mesenchymal_transition, GOMF_signaling_receptor_binding, and GOBP_cell_motility (5.19 × 10−33, 3.66 × 10−12 and 3.16 × 10−12, relatively)." (PMID 39456890, 2024). "After completion of radiotherapy an increase of positive CTC markers – especially the epithelial (CK19, EpCAM) and neuroendocrine (SYP, CHGA) transcripts was observed, which led us to the hypothesis of increased CTC shedding due to the disruption of the tumor by radiation therapy." (PMID 39305397, 2024). "Furthermore, EpCAM-CAR-T cells could also effectively kill tumour cells in vivo and significantly reduce the tumour volume." (PMID 39107717, 2024). "In situ sequencing also confirmed a consistent pattern: in EpCAMhigh tumor cell-dominated spots, compared to EpCAM-negative cell-dominated spots, there was a more frequent expression of the CD133/PROM1 gene along with the transcription factor genes OCT4/POU5F1, KLF4, and MYC." (PMID 39456890, 2024). "Hence, we hypothesized that C22orf46 knockout may promote cell surface presentation of the tumor antigens Her2, EGFR, and EpCAM, providing an explanation for the observed phenotype." (PMID 38228372, 2024). "The findings of our study indicate that EpCAM-positive EVs levels in ascites of patients with advanced HGSC have potential as prognostic biomarkers for predicting early recurrence and thereby likelihood of more aggressive tumor biology and development of chemoresistance." (PMID 38928484, 2024). "The oncogene-enriched type mainly involves upregulated genes related to tumor cell proliferation and invasion, including Claudin3 (CLDN3), Claudin4, serine peptidase inhibitor Kazal type 1 (SPINK1), epithelial splicing regulatory protein 1 (ESRP1), and epithelial cell adhesion molecule (EpCAM)." (PMID 38611084, 2024). "Epithelial cell adhesion molecule (EpCAM) negative CTCs (EpCAM-CTCs) refer to CTCs that do not express EpCAM, and EpCAM- CTCs and EpCAM positive CTCs (EpCAM + CTCs) have different biological characteristics, that is to say, tumor heterogeneity." (PMID 39280341, 2024). "It is possible that the marked interindividual heterogeneity, manifested by different combinations of EpCAMhigh, EpCAMlow, and EpCAM-negative tumor cells (in both primary tumors and CTCs), may be an independent criterion associated with metastasis." (PMID 39456890, 2024). "However, the expression of CD133/PROM1, OCT4/POU5F1, KLF4, and MYC occurred more frequently compared to EPCAM-negative tumor spots." (PMID 39456890, 2024). "Our findings indicate that EpCAM-positive EVs in ascites of patients with advanced HGSC have the potential to serve as prognostic biomarkers for predicting early recurrence and thereby likelihood of more aggressive tumor biology and development of chemoresistance." (PMID 38928484, 2024).
tumor (continued). "Genetic deletion of HLA class I cell surface molecules augmented ADCP by anti-epithelial cell adhesion molecule (EpCAM) or anti-epidermal growth factor receptor (EGFR) antibodies, suggesting that the HLA class I:LILRB1 axis may compromise the therapeutic efficacy of tumor targeting antibodies." (PMID 37781391, 2023). "Moreover, spatial analysis of the CD44v6 and EpCAM cancer stem cell (CSC) markers within the CD8/NOS2/COX2 expression landscape revealed positive correlations between EpCAM and inflamed stroma-restricted CD8+NOS2+COX2+ phenotypes at the tumor/stroma interface in deceased patients." (PMID 38187532, 2023). "Thus, EpCam does not reflect the phenotype of cancer-initiating cells and further studies of the role of this glycoprotein in tumor initiation and progression, as well as the possibility of its application in diagnostics, is required." (PMID 36875773, 2023). "Several promising CAR-T cell tumor targets were identified, including Glypican-3 (GPC3), alpha-fetoprotein (AFP), NK group 2 member D ligand (NKG2DL), Mucin 1 glycoprotein 1 (MUC1), Epithelial cell adhesion molecule (EpCAM), Claudin18.2 (CLD18), CD147, CD133, HBV surface protein, and c-MET." (PMID 36980692, 2023). "To determine whether the morphology of the organoids was linked to the EMT continuum, we performed label-free quantitative proteomic analysis of lysates generated from the YFP + EpCAM+ primary tumors, YFP + EPCAM- primary tumors, and YFP + secondary tumor organoids." (PMID 36828915, 2023). "EpCAM should not be regarded as tumor-specific in UC without patient-specific predictive testing." (PMID 37154925, 2023). "Thus, the cytotoxic activity of CAR-T cells was directed only against tumor cells in which both EpCAM (or B7-H3) and ROR1 antigens were present, with no detrimental effect on normal ROR1+ cells." (PMID 36873868, 2023). "In our pilot experiment, we performed comparative analysis of CD117, EpCam and CD81 abundance on EVs isolated from ascitic fluids of the patient with primary tumor (ovarian papillary cystadenocarcinoma) and of the same patient with post-treatment tumor relapse." (PMID 36875773, 2023). "Thus, at least in some cancers, the value of EpCam expression does not correlate with aggressiveness of the tumor and its role in cancer biology needs to be further studied." (PMID 36875773, 2023). "Neither overall nor fragment-specific EpCAM expression showed relevant tumor specificity." (PMID 37154925, 2023). "Additionally, lower EPCAM, β-catenin, β-catenin (in the nucleus), c-Myc, and SOX2 protein levels were seen in SiHa-SNAI2-cell-derived xenografted tumor tissues compared to SiHa-Vec-cell-derived xenografted tumor tissues (p < 0.05)." (PMID 36674577, 2023). "Out of all analyzed antigens, only the expression of EpCAM was significantly increased in tumors that disseminated into lymph nodes; the levels of EpCAM separated patients that had lymph nodes involved at the time of primary tumor resection from those that had not lymph node metastases present." (PMID 36550781, 2023). "The tumours that did not respond were enriched for EMT tumour cells (K14−VIM+ or EPCAM−)." (PMID 36949199, 2023). "However, these researchers indicated that their murine EpCAM-redirected CAR-Ts recognized and became activated by EpCAM expressed on non-malignant tissues leading to on-target off-tumor toxicities." (PMID 38146364, 2023). "shRNA KD of Rhoj and Rhoq in EPCAM+ tumour cells did not change their response to chemotherapy." (PMID 36949199, 2023). "Neither data type nor the pathological subtypes demonstrated general tumor specificity of EpCAM." (PMID 37154925, 2023). "However, the role of EpCam in tumor initiation, progression, and therapy resistance in not well established." (PMID 36875773, 2023). "Importantly, there was no indication of relevant tumor specificity, neither for EpCAM-NT and EpCAM-NT-G which were quantifiable in fewer samples due to the lower sensitivity of E144." (PMID 37154925, 2023).
tumor (continued). "As in other tumor entities, the accumulation of genomic alterations results in an increasing degree of cellular atypia and a reduced expression of a continuously growing number of physiologically expressed genes – such as TROP2 and EpCAM - in high grade tumors." (PMID 38282671, 2023). "In this study, PFC-based immunophenotypical characterization of circulating EVs indicated that blood levels of total, CD133+ and EPCAM+ EVs are higher in patients with advanced CRC as compared to healthy controls, indicating that this increase reflects phenotypic changes induced by the tumor." (PMID 35267665, 2022). "EpCAM+EGFR+ events detected in healthy donor blood samples showed no tumor cell-like morphology." (PMID 36613466, 2022). "Furthermore, these engineered bacteria exerted tumor antigen targeting in cell cultures, whereby strong and highly specific adhesion to HEK293 cells overexpressing the tumor antigens EpCAM or HER2 was achieved, particularly by the EpCAM-targeting L. lactis strains." (PMID 35155394, 2022). "Circulating tumor cells (CTCs) are cells shed from a primary tumor into the vasculature with an intact viable nucleus, a positive cytokeratin, epithelial cell adhesion molecule (EpCAM) and a negative CD45 molecule." (PMID 35292091, 2022). "Furthermore, the nanoparticle formulation showed significantly higher tumor growth inhibition compared to non-targeted particles or free DOX suggesting a beneficial effect of EpCAM aptamer mediated targeting." (PMID 35673581, 2022). "The current biomarkers used for tumor cell isolation, e.g., EpCAM, are not effective due to their insensitivity and low specificity, which leads to the requirement of mechanistic studies on expression regulation of these tumor biomarkers." (PMID 36077658, 2022). "The TelomeScan may be more applicable for the detection of EMT tumor cells given that it is not influenced by the level of EpCAM expression." (PMID 35962400, 2022). "Anti-EpCAM CAR T-cells used against CRC cells and models exhibited cytotoxic lysis of the targeted cells that secreted cytotoxic cytokines, including IFN-γ and tumor necrosis factor-alpha (TNF-α), resulting in tumor growth and development in xenograft mouse models." (PMID 35814023, 2022). "Furthermore, the low detection frequency of circulating tumor cells (CTCs) in HNSCC with EpCAM‐based methods also indicates low or absent EpCAM expression in DTCs." (PMID 34719102, 2022). "Pre-clinical SPECT/CT imaging indicated a rapid accumulation and relatively high uptake in subcutaneous EpCAM-positive HT-29 tumours but EpCAM-negative HL-60 tumours could not be imaged." (PMID 36182995, 2022). "However, this study aimed to focus on the removal of EpCAM-expression cancer cells, independent of the entity of the tumor cell." (PMID 35890293, 2022). "However, EpCAM expression on the surface of epithelial tumour cells is highly heterogeneous, and some types of cancer cells do not express EpCAM." (PMID 34611964, 2022). "This method has a limitation because although EpCAM is expressed in most epithelial-derived cells but not in blood cells, tumor cells who undergo endothelial-mesenchymal transition are not detected; furthermore, the absence of standardization limits the diffusion of CTC detection." (PMID 36230554, 2022). "It is obvious that immuno‐biochemical techniques targeting antigens like EpCAM are not infallible for all tumor entities or heterogeneous CTC populations, especially CTCs undergoing epithelial‐mesenchymal transition (EMT) which is closely linked to invasive metastasis." (PMID 35573135, 2022).
tumor (continued). "created a non-immunomodulating bsApt that targeted CD44 and EpCAM, two tumor cell surface markers that are overexpressed in ovarian cancer and are associated with malignant ascites, chemoresistance, decreased survival, and epithelial-to-mesenchymal transition (EMT)." (PMID 35141049, 2022). "In addition, tumor growth was reduced by combined treatment with AKT and mTOR inhibitors in an orthotopic xenograft mouse model of an EpCAM+ HCC cell line (Huh7) and primary patient-derived EpCAM+ HCC cells (HCC1) as well as a CD90+ HCC-related cell line (SK-HEP1) in vivo." (PMID 35454789, 2022). "Thus, co-expression of CD166 with EpCAM (but not alone) was accompanied by a significantly elevated tumor aggressive behavior." (PMID 35016698, 2022). "Comparisons with other techniques, such as CellSearch (EpCAM) or Epispot (negative depletion), as well as specificity analyses, have confirmed the ability of the wire to capture a large number of rare tumor cells from the blood." (PMID 35054482, 2022). "Importantly, the enrichment of CD31 and the absence of EpCAM indicate that our EV preparations contain endothelial EVs that are not contaminated by EVs derived from tumour cells." (PMID 35656866, 2022). "Immunostaining for TILs (CD8+) and tumor cells (EpCAM+) and time-lapse confocal microscopy was combined with SHG imaging for the tumor stroma to reveal that, as lung PCTS, TILs in ovarian PCTS preferentially accumulated within stroma regions and were less abundant in tumor islets." (PMID 35466279, 2022). "Binding of E-cadherin on PDX tumor cells to CD103+ CD8+ TRM cells may sequester these TILs within the tumor implant, and the expression of E-Cadherin by EpCAM+ tumor cells was not affected by trametinib treatment." (PMID 35740548, 2022). "This largely limits the sensitivity of Cellsearch system for EpCAM negative tumor cells." (PMID 36091119, 2022). "In addition, some scholars have found that CD24+/CD44+- EPCAM+ cell subsets have specific gene expression profiles, and these stemness-related cell subclones in HCC enable tumor cells to acquire great genetic richness, leading to the failure of HCC targeted therapy." (PMID 36303541, 2022). "Proteins within tumour compartments consistent with longer OS included PD-L1 (HR=0.53, p=0.023), FOXP3 (HR=0.5, p=0.026), GITR (HR=0.51, p=0.036), SMA (HR=0.59, p=0.043), while EPCAM (HR=1.7, p=0.045), and CD95 (HR=4.9, p=0.046) expression were associated with shorter OS." (PMID 35083152, 2021). "Taken together, it seems that the risk /benefit ratio using Catuvab regarding the potential contamination with residual EpCAM negative tumor cells might be acceptable, but needs further clinical evaluation." (PMID 34715784, 2021). "WT EpCAM, but not C66Y EpCAM, inhibits tumor cell invasion in vitro and lung metastases in vivo." (PMID 33980181, 2021). "Overall, detection systems based only on epithelial-cell surface markers, such as EpCAM, and cytoskeletal proteins, such as CKs (Cytokeratin), are not ideal for the characterization of all CTC subpopulations, which is important in order to fully assess tumor heterogeneity." (PMID 34439363, 2021). "However, knocking down EpCAM failed to significantly alter radiation responses in Brca1-mutant tumor cells (data not shown), suggesting that, although EpCAM is a functional biomarker candidate, it not a promising target of therapeutics." (PMID 33767581, 2021). "On the contrary, mTOR and NOTCH inhibitors (e.g., rapamycin and DAPT) reduce the CD133+/EpCAM+ enrichment of both the epithelial and mesenchymal-like HCC cells, showing that rapamycin prior to sorafenib administration is the best option able to reduce the formation of tumor spheres." (PMID 34572776, 2021). "In addition to pan-CK, the majority of EpCAM-negative objects carried other tumor markers indicating a tumor origin." (PMID 33801459, 2021). "EPCAM showed no significant change in expression between tumour and CTCs." (PMID 34206049, 2021).